HMGB1 (high mobility group box 1)
Diseases named in the same sentence as HMGB1 in open-access papers (continued):
Sharing a sentence is not in itself a finding about the gene and the disease.
systemic lupus erythematosus (continued). "Administration of a neutralising monoclonal anti-HMGB1 antibody to the lupus-prone BXSB mice attenuates proteinuria, glomerulonephritis, circulating anti-dsDNA, immune complex deposition and levels of cytokines in serum." (PMID 26596890, 2015). "From a lupus perspective, HMGB1, a DNA-binding protein with alarmin potential when released into the extracellular space, has received considerable interest in recent years, as evidenced by the number of review articles written on this topic." (PMID 23248629, 2012). "HMGB1 probably has the most momentum presently for use as a biomarker in the clinical care of lupus patients—especially in the context of nephritis—but confirmation in additional patient populations is needed." (PMID 23248629, 2012). "As our study was of limited size, additional extended studies will be required to study the role of HMGB1 as a biomarker for renal disease activity in patients with lupus." (PMID 22348591, 2012). "Notably, the kidney IgG deposits in cKO mice hint at a breakdown in tolerance, reminiscent of HMGB1’s role in suppressing lupus-like autoimmunity by regulating DNA sensing in B cells." (PMID 40985892, 2025). "Additionally, HMGB1 has emerged as a novel marker for systemic lupus erythematosus (SLE), with elevated levels detected both in the serum and skin lesions of SLE patients." (PMID 39769332, 2024). "Interestingly, HMGB1 activity plays a markable role in a variety of lupus phenotypes, including LN, neuropsychiatric lupus, and skin lesions." (PMID 35529869, 2022). "Administration of an HMGB1 antagonist alleviated the disease in experimental lupus models." (PMID 33925132, 2021). "Thus, soluble biglycan in inflammatory renal diseases, HMGB1 in systemic lupus erythematosus, or S100 proteins in several inflammatory conditions are some examples." (PMID 33537330, 2020). "The HMGB1 (high mobility group box 1) protein, which binds DNA and the lupus autoantigen released under inflammation, can induce the activation of NF-κB in a TLR2-dependent and TLR4-RAGE-dependent manner in mononuclear phagocytes and neutrophils as well as in mesangial cells." (PMID 32933213, 2020). "Previous study revealed that HMGB1 inhibition by a specific antibody could ameliorate albuminuria in MRL/lpr lupus-prone mice." (PMID 31303606, 2019). "Indeed, elevated concentrations of HMGB1 are observed in the sera, urine, kidney tissues, and skin lesions of patients with lupus." (PMID 28649578, 2017). "Interestingly, autoantibodies against HMGB1 have also been described in patients with systemic lupus erythematosus (SLE), but their clinical implications remain elusive." (PMID 26596890, 2015). "Furthermore, HMGB1 has been found to be significantly elevated in lupus sera and identified as one of the components in DNA-containing immune complexes that enhance proinflammatory cytokine production." (PMID 26078984, 2015). "However, further studies are needed to evaluate the clinical significance of measuring urinary HMGB1 and its value as a biomarker in lupus patients with renal involvement." (PMID 22892043, 2012). "Apoptosis or clearance of apoptotic cells has been reported as an important pathophysiological characteristic in autoimmune diseases such as systemic lupus erythematosus, therefore targeting HMGB1 might have an important role on the inflammation control." (PMID 22888407, 2012). "Elevated HMGB1 expression has previously been demonstrated in lupus patients with cutaneous photoinduced inflammation, in whom cytoplasmatic and extracellular HMGB1 were detected in biopsies from the most clinically active skin lesions in comparison with inactive or non-lesional skin." (PMID 22348591, 2012). "In addition, HMGB1 has been found to be significantly elevated in lupus sera and has been regarded as one of the components in DNA-containing immune complexes that enhance cytokine production through TLR9 or RAGE ligation." (PMID 21548924, 2011).
systemic lupus erythematosus (continued). "Additionally, in an experimental model of systemic lupus erythematosus HMGB1 was detected in circulating nucleosome complexes and the necessity of HMGB1 for these complexes to be immunogenic and to induce production of anti-DNA antibodies were demonstrated." (PMID 21871094, 2011). "Recently, we have also shown that HMGB1-nucleosome complexes released from late apoptotic cells are inflammatory and lead to the production of autoantibodies against histones and DNA, and thus the pathogenesis of systemic lupus erythematosus (SLE)." (PMID 19641621, 2009). "Wang also demonstrated that PA alleviates depressive-like symptoms in systemic lupus erythematosus (SLE)-induced MRL/lpr mice by suppressing HMGB1/TLR4/NF-κB signaling." (PMID 41535967, 2026). "HMGB1 has anti-DNA effects on rheumatoid arthritis, systemic lupus erythematosus (SLE), and myositis through the formation of immunostimulatory complexes with proinflammatory cytokines." (PMID 34072941, 2021). "HMGB1 has been studied extensively because it has a clear relationship with insulin resistance and diabetes, obesity and polycystic ovarian syndrome, as well as immunological conditions such as systemic lupus erythematosus (SLE), RA and infectious diseases, including in COVID-19." (PMID 34440629, 2021). "HMGB1 has also been reported to skew macrophage polarization towards a pro-inflammatory M1-like phenotype in an experimental model of autoimmune myocarditis and systemic lupus erythematosus (SLE), and may contribute to the pathogenesis of these conditions." (PMID 32664328, 2020). "HMGB1 was found to drive DNA demethylation in CD4+ T cells of systemic lupus erythematosus (SLE) patients." (PMID 33029541, 2020). "The first observation of colocalization of HMGB1 with NETs was reported in systemic lupus erythematosus (SLE), wherein HMGB1 was detected in complexes with nucleosomes and DNA and signified a potential marker for disease severity." (PMID 32731558, 2020). "Serum levels of HMGB1 were measured in the sera of children with MAS developing as a complication of sJIA or of systemic lupus erythematosus (SLE)." (PMID 30766533, 2019). "In particular, in SLE patients, serum HMGB1 levels correlated with systemic lupus erythematosus disease activity index (SLEDAI), proteinuria, and anti-ds-DNA antibodies, showing a negative correlation with complement C3." (PMID 29410969, 2017). "Circulating increased HMGB1 levels have been shown during severe sepsis, pneumonia, systemic lupus erythematosus (SLE), and in the synovial fluid of patients with rheumatoid arthritis." (PMID 29410969, 2017). "Extracellular high-mobility group box 1 (HMGB1) acts as an alarmin and has been shown to be a biomarker of disease activity as well as an autoantigen in systemic lupus erythematosus (SLE) and, possibly, in AAV." (PMID 24007972, 2013). "In systemic lupus erythematosus (SLE), serum HMGB1 has been shown to be a biomarker of disease activity, especially in patients with lupus nephritis." (PMID 24007972, 2013). "Indeed, we could show that IgG depletion decreased the amount of HMGB1 in sera from lupus patients, suggesting that at least part of HMGB1 is complexed with anti-HMGB1 antibodies." (PMID 21548924, 2011). "Thus, it is likely that PUFAs and their anti-inflammatory products such as lipoxins, resolvins, protectins and maresins inhibit the production of various pro-inflammatory molecules including MIF and HMGB1 and thus, suppress inflammation in diseases such as lupus and rheumatoid arthritis." (PMID 21569625, 2011). "Autophagy SGs in elastase induced AAA aortas had functional pathways, namely, neuroinflammation signaling, high mobility group box 1 (HMGB1) signaling, IL-17 signaling, systemic lupus erythematosus in B cell signaling, and cardiac hypertrophy signaling." (PMID 35320939, 2022).
systemic lupus erythematosus (continued). "High amounts of HMGB1 and HSP 70 for example have been identified in the synovia of rheumatoid arthritis patients, dsDNA complexes induce interferon signaling in dendritic cells and even serve as diagnostic criteria of systemic lupus erythematosus (SLE)." (PMID 30828327, 2019). "In pristane-induced lupus mouse model, TLR2−/− mice show lower ANA levels and reduced lupus pathogenesis, together with a reduced level of HMGB1, a well-known endogenous TLR ligand." (PMID 26068236, 2015). "Since HMGB1 is an essential part of the immune complexes in lupus and since the immune complexes lead to immune activation via a pathway involving RAGE, the elevation of HMGB1 and the simultaneous decline of sRAGE could favour HMGB1-RAGE signalling as an important pathogenic mechanism." (PMID 25516724, 2014). "α-defensins 1 and 3 were identified in the proteomic analysis of PMA-induced NETs, while both HMGB1 and α-defensins/HNP have been described in the context of lupus NETs." (PMID 23248629, 2012). "Similarly, treatment with an HMGB1 monoclonal neutralizing antibody can alleviate the phenotype of MRL/lpr and BXSB Lupus mice, but it has also been shown to be ineffective in MRL/lpr mice." (PMID 39967676, 2025). "In contrast, a different study has recently reported that treatment with an anti-HMGB1 monoclonal antibody (mAb) does not affect lupus activities in MRL/lpr mice." (PMID 28649578, 2017). "To elucidate this discrepancy, we examined the efficacy of anti-HMGB1 mAb to determine whether it ameliorates lupus activities, including nephritis and serological abnormalities, in MRL/lpr lupus-prone mice." (PMID 28649578, 2017). "Our data demonstrate that HMGB1 binds to Gadd45a and may be involved in DNA demethylation in CD4+ T cells during lupus flare." (PMID 24082908, 2013). "Previous studies have shown increased HMGB1 expression in skin lesions of patients with SLE, thus indicating that HMGB1 may be an important mediator of inflammation in target organs in lupus." (PMID 22348591, 2012). "We found a clear tissue staining for HMGB1 in LN and this staining was absent in non-lupus control renal tissue." (PMID 22348591, 2012). "As apoptotic cells accumulate in systemic lupus erythematosus (SLE), HMGB1 levels might be increased in SLE." (PMID 21548924, 2011). "In the case of HMGB1, this alarmin is involved in many non-pathogen-mediated diseases including sepsis, arthritis, atherosclerosis, systemic lupus erythematosus (SLE), cancer, and hepatitis." (PMID 22399974, 2009). "For instance, in patients with systemic lupus erythematosus (SLE), autoantibodies directed against double—stranded DNA (dsDNA) and nucleosomes can trigger the activation of DCs via TLR2 when complexed HMGB1." (PMID 40877572, 2025). "However, a recent study has reported that the anti-HMGB1 antibody did not affect lupus activities in MRL/lpr mice." (PMID 28649578, 2017).
Arthritis (94 papers, 2005 to 2025). Inflammation of a joint. "Polyclonal anti-HMGB1 antibodies have also been implicated in confronting against inflammatory upsurge, arthritis, acute pancreatitis, and inflammatory bowel disease." (PMID 39682695, 2024). "HMGB1 has also been implicated in the periphery, with its release from neurons linked to localized inflammation in animal models of nerve injury and arthritis." (PMID 35573828, 2022). "At the same time, HMGB1 can induce systemic inflammatory responses such as fever, arthritis, acute lung injury, anorexia and weight loss." (PMID 33925132, 2021). "In conclusion, we report the novel finding that HMGB1 can be regulated by proteases associated with inflammation and arthritis." (PMID 33391251, 2020). "In order to assess the biological relevance of our in vitro findings we first verified the presence of the investigated proteases during an inflammatory condition where HMGB1 is regarded as a pathogenic mediator; arthritis." (PMID 33391251, 2020). "HMGB1 levels are increased in the plasma of diabetic patients, and HMGB1 is implicated in chronic pain associated with arthritis, and traumatic and chemotherapy-induced neuropathic pain, probably through RAGE activation." (PMID 29930087, 2018). "It is well known that HMGB1 is released at the site of joint inflammation and that the injection of HMGB1 into a normal joint causes development of arthritis." (PMID 25516724, 2014). "The study of hypoxia in RA patients showed that hypoxia and HMGB-1 were associated with development of arthritis." (PMID 23834772, 2013). "TNFα and high mobility group box chromosomal protein 1 (HMGB1) are two potent proinflammatory cytokines implicated as important mediators of arthritis." (PMID 18582368, 2008). "High mobility group box chromosomal protein 1 (HMGB1), a nuclear DNA-binding protein, proved recently to be a potent proinflammatory cytokine implicated as an important mediator of arthritis." (PMID 18582368, 2008). "Previous studies have confirmed that HMGBl is highly expressed in the synovium of patients with RA, and anti-HMGB1 antibody can inhibit the inflammatory response caused by HMGB1, reduce the damage to joint tissue, and effectively alleviate arthritis caused by HMGB1." (PMID 35956875, 2022). "HMGB1 could induce systemic inflammatory reactions, such as cold, arthritis, anorexia, or weight loss." (PMID 35733802, 2022). "In vivo, HMGB1 can initiate systemic inflammation that can be associated with fever, epithelial barrier dysfunction, endothelial cell activation, acute lung injury, anemia, cognitive dysfunction, arthritis, anorexia and even death." (PMID 33925132, 2021). "A mechanism for the pathogenic role of HMGB1 in arthritis could thus be through enhancement of inflammatory and destructive mechanisms induced by other proinflammatory mediators present in the arthritic joint." (PMID 21871094, 2011). "The purpose of the present study was to investigate whether the arthritis-inducing effect of HMGB1 is dependent on TNFα expression in vivo and to assess whether TNFα deficiency affects a proinflammatory cytokine response to HMGB1 in vitro." (PMID 18582368, 2008). "In collagen-induced arthritis and collagen antibody-induced arthritis mouse models, ferroptotic M2 macrophages released HMGB1, which engaged TLR4 and activated STAT3 signaling in M1 macrophages, fueling inflammatory amplification loops." (PMID 40722994, 2025). "Anti-HMGB1 was shown to be protective in arthritis models, and in high-fat diet-induced atherosclerosis in ApoE-/- mice." (PMID 40216765, 2025). "Neutralizing the endogenous spinal TLR4 ligand HMGB1 with antibodies or suppressing microglial activation reverses mechanical hypersensitivity in female mice with collagen antibody-induced arthritis." (PMID 41511304, 2025). "HMGB1 certainly plays an important role in IgAV, as logistic regression identifies it as significant in predicting IgAV and arthritis as well." (PMID 38673968, 2024).
Arthritis (continued). "In the same study, using conditional DRG nociceptor TLR4 knockout animals demonstrated that HMGB1 mediates arthritis pain through TLR4 signaling in both sexes." (PMID 39439003, 2024). "In models of sciatic nerve injury and arthritis, nociceptor-restricted HMGB-1 ablation resulted in decreased inflammation and ameliorated pathology." (PMID 37006298, 2023). "Increased extracellular HMGB1 expression has been reported in several sterile injury models, including collagen-induced arthritis or during the spontaneous development of arthritis in mice." (PMID 35229226, 2022). "Extracellular HMGB1 takes a part of a coupling factor between hypoxia and inflammation in arthritis and localizes preferentially to regions of tissue hypoxia in arthritic lesions." (PMID 36081910, 2022). "Blocking the action of peripheral HMGB1, however, only reversed collagen antibody-induced arthritis-mediated hypersensitivity in males." (PMID 32796317, 2021). "Monoclonal anti-HMGB1 antibody significantly ameliorates the clinical courses and partially prevents joint destruction in collagen type II-induced arthritis and spontaneous arthritis model." (PMID 33925132, 2021). "Here, we used the collagen antibody-induced arthritis (CAIA) model to investigate if blockade of peripheral HMGB1 attenuates pain-like behavior in a sex-dependent fashion." (PMID 32796317, 2021). "Experimental models of arthritis showed inhibitory effects of anti-HMGB1 antibodies on the development of synovial inflammation." (PMID 33776579, 2021). "In this study, we addressed the role of peripheral HMGB1 and explored if sex contributes differentially to nociception in arthritis." (PMID 32796317, 2021). "At the onset of arthritis, levels of serum HMGB1 were significantly elevated in children with systemic JIA compared with healthy controls, the ReA group, and other JIA subgroups (P < 0.0001)." (PMID 34247641, 2021). "We found Hmgb1 expression to be elevated in the ankle joints of male and female mice subjected to collagen antibody-induced arthritis." (PMID 32796317, 2021). "Spinal high mobility group box 1 protein (HMGB1) plays crucial roles in arthritis-induced pain; however, the involvement of peripheral HMGB1 has not been examined previously." (PMID 32796317, 2021). "Neutralizing HMGB1 antibodies or truncated HMGB1-derived A-box proteins are currently evaluated in collagen-induced arthritis rodent models." (PMID 33537330, 2020). "Intra-articular administration of recombinant HMGB1 into the knee joints of mice induces destructive arthritis, while administration of monoclonal anti-HMGB1 antibody or the antagonistic box A peptide can ameliorate inflammatory symptoms." (PMID 33391251, 2020). "Although the levels of each protease did not correlate with the levels of HMGB1, our study suggests that proteolytic cleavage of HMGB1 can be a downregulatory mechanism of HMGB1 activity during arthritis." (PMID 33391251, 2020). "It has also been reported that an intra‐articular expression of HMGB1 exacerbated synovitis in mice, while neutralized HMGB1 inhibited the progression of experimental arthritis." (PMID 32686306, 2020). "Herein we show that enzymes present in arthritis-affected joints process HMGB1 into smaller peptides in vitro." (PMID 33391251, 2020). "HMGB1 is known to function as a coupling factor between hypoxia and inflammation in arthritis, and this inflammatory response is modulated by microRNAs (miRNAs), with miR-107 expression downregulated during hypoxia." (PMID 30704538, 2019). "While under pathological conditions, such as diabetic oxidative stress, periodontitis, and arthritis, an uncontrolled expression and release of HMGB1 can lead to an overwhelming of bone resorption." (PMID 31929852, 2019). "Blocking HMGB1 activity is therapeutic in arthritis, since administration of either anti-HMGB1 or A-box of HMGB1 in collagen type II-induced arthritis significantly attenuated the severity of disease." (PMID 31560698, 2019).